TRIB3 (tribbles pseudokinase 3)
Diseases named in the same sentence as TRIB3 in open-access papers (continued):
Sharing a sentence is not in itself a finding about the gene and the disease.
colorectal cancer (39 papers, 2009 to 2025). A primary or metastatic malignant neoplasm that affects the colon or rectum. "Increase in expression of PHPT1, PPP2R5D, and two TRIB3 transcripts indicates that tumor-associated changes in alternative splicing can affect glucose metabolism in colorectal cancer." (PMID 28105922, 2016). "TRIB3 is a prognosis hallmark of colorectal cancer, activated under hypoxic conditions." (PMID 34249670, 2021). "In various tumors, such as colorectal cancer, lung cancer, and glioma, TRIB3 has been reported to physically interact with and activate β‐catenin." (PMID 39665272, 2025). "Several studies reveal that TRIB3 promoting the progression of lung cancer, clear cell renal cell carcinoma, colorectal cancer and acute myeloid leukaemia, however, few is known about the regulation of TRIB3 in BC." (PMID 38307969, 2024). "In colorectal cancer, TRIB3 plays an inhibitory role while also suppressing CD8 T cell infiltration and promoting glioblastoma cell stem-like properties through interactions with beta-catenin that facilitate tumor growth." (PMID 38090559, 2023). "Tribbles pseudo-kinase 3 (TRIB3) can then interact with β-catenin/TCF4 to increase stem cell features of colorectal cancer stem cells and tumorigenesis." (PMID 37337284, 2023). "In fact, colorectal cancer patients with high TRIB3 protein and mRNA expression levels are likely to experience a recurrence of the disease and display poorer overall survival." (PMID 33920424, 2021). "In fact, colorectal cancer patients with high TRIB3 protein and mRNA expression levels are likely to experience a recurrence of the disease and displayed poorer overall survival." (PMID 33920424, 2021). "In colorectal cancer cells, TRIB3 interacts with TCF4 but also with β-catenin in a dose-dependent manner." (PMID 33920424, 2021). "The overexpression of TRIB3 in lung and colorectal cancer can regulate some important cancer signaling pathways." (PMID 34957220, 2021). "In this review, we discuss the state-of-knowledge for TRIB1, TRIB2 and TRIB3 in the development and progression of colorectal cancer." (PMID 34198908, 2021). "The importance of TRIB3 in cancer is supported by the finding that TRIB3 is also involved in the prognosis of colorectal cancer patients." (PMID 21864376, 2011). "Trib2 has been shown to be a repressor of FOXO in malignant melanoma, and Trib3 expression is altered in colorectal cancer." (PMID 21811619, 2011). "Previous studies have shown that TRIB3 controls the cell growth through ubiquitination-dependent degradation of other proteins, whereas its significance in the prognosis of colorectal cancer (CRC) is not yet fully understood." (PMID 19904274, 2009). "In lung cancer, TRIB3 has been reported to facilitate tumor progression by interacting with EGFR; Similarly, TRIB3 has been shown to enhance the stemness of cancer cells and drive the progression of colorectal cancer and glioma by interacting with β-catenin and TCF4." (PMID 39881875, 2024). "In colorectal cancer, immune evasion is related to Tribbles homolog 3 (TRIB3)." (PMID 39223632, 2024). "In addition, C646 enhances antitumour activity in colorectal cancer by blocking TRIB3 acetylation and promoting TRIB3 degradation." (PMID 36979352, 2023). "Moreover, TRIB3 has been reported to affect the immune infiltration of NK, T, and B cells in colorectal cancer." (PMID 38235126, 2023). "Glycolysis activates the HIF1α/Tribbles pseudokinase 3 (TRIB3) signaling pathway, leading to activation of the β-catenin/Wnt signaling pathway and ultimately enhancing stem cell-like phenotype and cell invasion in colorectal cancer." (PMID 37124519, 2023). "A recent study demonstrated that tribbles pseudo-kinase 3 (TRIB3) induces and maintains stemness of colorectal cancer stem cells (CCSCs) by changing the homeostasis of CSCs’ self-renewal and differentiation, which is mediated by forming a positive feedback loop between TRIB3 and Wnt/β-catenin." (PMID 33898430, 2021).
colorectal cancer (continued). "Tribbles pseudokinase family members (TRIB1 (C8FW or SKIP1), TRIB2 (C5FW) and TRIB3 (NIPK, SKIP3 or LKW)) might be biomarkers of interest in colorectal cancer." (PMID 34198908, 2021). "TRIB3 can interact with β-catenin and transcription factor 4 in intestine cells to increase expression of genes that are relevant with cancer stem cells in colorectal cancer." (PMID 32457797, 2020). "Thus, tumor-associated changes in alternative splicing lead to overexpression of certain TRIB3 splice isoforms which can be involved in development of colorectal cancer." (PMID 28105922, 2016). "Tribbles pseudokinase 3 (TRIB3) can cooperate with STAT3 to increase VEGF-A expression and promote colorectal cancer angiogenesis." (PMID 38687357, 2024). "Previous research has confirmed that TRIB3 can inhibit CD8+ T cell infiltration and stimulate the immune evasion through inhibiting the STAT1-CXCL10 axis in colorectal cancer, which is consistent with our results." (PMID 37732314, 2023). "In addition, TRIB3 activated the Wnt-β-catenin signaling pathway via the C-terminal and N-terminal regions of the kinase-like domain in TRIB3, directly binding to β-catenin in colorectal cancer, indicating that activation of Wnt/β-catenin signaling by SALL4 may require TRIB3 expression." (PMID 35216168, 2022). "Additionally, TRIB3 interacts with β-catenin and TCF4 to increase the stem cell features of colorectal cancer stem cells and trigger tumorigenesis." (PMID 35726370, 2022). "Previous studies based on several cancer cells and animal models had found that the inactivation of TRIB3 regulated Akt pathway and enhanced tumor development, while FABP1 was significantly downregulated in some subtypes of colorectal cancer due to the influence of immune microenvironment." (PMID 34957220, 2021). "ICG-001 activates an early ER stress pathway including activating transcription factor 4 (ATF4), DNA damage inducible transcript 3 (DDIT3), and tribbles pseudokinase 3 (TRIB3) in sensitive as opposed to resistant colorectal cancer cell lines." (PMID 29290987, 2017). "Moreover, TRIB3 induces immune evasion and reduces CD8+ T cell infiltration in colorectal cancer." (PMID 37189176, 2023). "However, TRIB3 was up-regulated in CRC samples, gastrointestinal and colorectal cancer cell lines." (PMID 28105922, 2016). "We studied the TRIB3 gene in 202 paired cancerous and non-cancerous regions of CRC, as well as 7 colorectal cancer cell lines and 15 other gastrointestinal cancer cell lines." (PMID 19904274, 2009).
Insulin resistance (30 papers, 2012 to 2025). Increased resistance towards insulin, that is, diminished effectiveness of insulin in reducing blood glucose levels. "These three miRNAs regulate genes associated with pancreatic cancer (Bcra2) and insulin resistance (Pck2 and Trib3) and regulate the expression levels of genes (Rela and Fos) among shared pathways." (PMID 39022651, 2024). "A recent report showed that compared to healthy subjects, TRIB3 level was significantly increased in the plasma of diabetic patients, and high TRIB3 level was associated with fasting blood glucose and insulin resistance." (PMID 38733632, 2024). "The pseudokinase Tribbles 3 (TRIB3) has been implicated in a number of metabolic processes such as modulating lipid and glucose metabolism, promoting insulin resistance, and inhibiting adipocyte differentiation." (PMID 36158793, 2022). "The Q84R variant of the human TRIB3 gene has been associated with insulin resistance, altered insulin secretion and with increased cardiovascular risk but the molecular mechanisms behind these associations are poorly understood." (PMID 36158793, 2022). "By contrast, fasting glucose levels (P = 0.02) and HOMA-IR index (P = 0.03) of insulin resistance were significantly associated with TRIB3 Q84R genotype." (PMID 34051802, 2021). "Nutrient starvation induces liver TRIB3 expression and overexpression of TRIB3 has been implicated in insulin resistance in animal models as well as in humans." (PMID 30987128, 2019). "The Trib3 SNP associated with insulin resistance results is a missense mutation, resulting in a change from a polar amino acid residue glutamine (Q) at position 84 in the conserved kinase-like domain to a basic one (R)." (PMID 29025897, 2017). "A prevalent single nucleotide polymorphism (dsSNP ID: rs2295490) in the human TRIB3 coding sequence predisposes carriers to early onset insulin resistance and early onset Type 2 diabetes." (PMID 29025897, 2017). "The TRIB3 SNP associated with insulin resistance results in a missense mutation, changing a polar amino acid glutamine (Q) at position 84 in the conserved kinase-like domain to basic arginine (R)." (PMID 29025897, 2017). "Though some evidence contradicted these early findings, the notion that Trib3 regulates insulin signaling was bolstered by the identification of a human Q84R SNP in Trib3 associated with insulin resistance and type 2 diabetes." (PMID 25329475, 2014). "In humans, TRIB3 has also been associated with insulin resistance and T2DM, accompanied by enhanced inhibition of insulin signalling and AKT/PKB activation in different tissues, including the β cells." (PMID 24650557, 2014). "The TRIB3 gene codes for a tribbles protein, which has been associated with the control of fatty acid synthesis and insulin resistance as well as regulating plasma triglyceride and HDL cholesterol levels in human species." (PMID 24295214, 2013). "Finally, the TRIB3 Q84R variant is associated with enhanced insulin resistance, and the relative contributions of altered glucose homeostasis versus impaired efferocytosis to the accelerated atherosclerosis phenotype in patients remain to be tested." (PMID 41186004, 2025). "In addition, in the context of inflammation and cardiovascular disease, loss of TRIB3 has been implicated in the development of diabetic atherosclerosis ameliorating insulin resistance and reducing macrophage apoptosis via modulating AKT phosphorylation." (PMID 36158793, 2022). "Functional TRIB3 Q84R polymorphism has been associated with insulin resistance." (PMID 23245314, 2012). "Interestingly, TRIB3 has been shown to be higher in the skeletal muscle of insulin resistant individuals compared to insulin sensitive individuals, and has been directly associated with whole‐body insulin resistance and high fasting plasma glucose." (PMID 32562350, 2020).
Insulin resistance (continued). "In addition, because insulin resistance is the physiopathologic foundation of more than one metabolic syndrome, TRIB3 gene may also be associated with high blood pressure." (PMID 24414038, 2014). "Furthermore, it has been demonstrated that the TRIB3 gene, especially the R84 variant, could help identify individuals at risk for insulin resistance and carotid atherosclerosis risk by determining carotid intima-media thickness (IMT)." (PMID 23245314, 2012). "TRIB3 (a mammalian tribbles homolog, also known as TRIB3/NIPK, gene ID 57761), has been reported by most studies, although not all studies, implicated in the regulation of insulin signal transduction by binding to and inhibiting Akt phosphorylation and to play a role in insulin resistance." (PMID 23245314, 2012). "In a model of diabetic atherosclerosis using ApoE/Ldldr double knockout mice fed with high fat and high sugar diet, siRNA-depletion of Trib3 led to a reduction in insulin resistance and atherosclerotic burden." (PMID 36158793, 2022). "Previous studies have demonstrated that TRIB3 is closely related to insulin resistance, metabolic disorders and vascular diseases." (PMID 36105108, 2022). "Activation of ER stress by tunicamycin and thapsigargin causes an increase in TRIB3 in C2C12 cells and skeletal muscle, which possibly mediates ER stress-induced insulin resistance." (PMID 35615361, 2022). "The 20p13-p12 chromosome region of TRIB3 is associated with human T2DM, affects insulin signaling by inhibiting Akt phosphorylation, and is overexpressed in a mouse model of insulin resistance." (PMID 36105108, 2022). "TRIB3 is increased in skeletal muscle of patients with type 2 diabetes mellitus known to be insulin resistant." (PMID 35615361, 2022). "TRIB3 is coupled to insulin resistance in oxidative stress, antioxidant stress, inflammation, adiponectin actions, peroxisome proliferator-activated receptor (PPAR) actions, SIRT1 actions, and insulin signal transduction." (PMID 33192545, 2020). "Knockdown of TRIB3 in skeletal muscle improved insulin sensitivity in a rat model for insulin resistance; however, rats exposed to short‐term exercise training improved glucose tolerance without changes in skeletal muscle TRIB3 protein." (PMID 32562350, 2020). "The fly insulin resistance model offers a convenient place to test the stage-, tissue- and diet-specific effects of these Trib3 SNPs." (PMID 29025897, 2017). "This study provides evidence for a potentially novel role for TRIB3 in injury‐induced skeletal muscle insulin resistance." (PMID 26818585, 2016). "Prior rodent studies, indicate that TRIB3 overexpression plays a major role in modulating whole-body insulin sensitivity and suggest a possible involvement in the pathogenesis of insulin resistance-related metabolic abnormalities." (PMID 24650557, 2014). "Our current study revealed that 26 week old ZDF diabetic rats showed pancreas overexpression of TRIB3 which, concurrently, showed insulin resistance and relative insulinopaenia." (PMID 24650557, 2014). "In the present study, we evaluated the association between 4 insulin resistance genes (ADIPOQ, LEPR, RETN, and TRIB3) and both T2DM and hypertension." (PMID 24414038, 2014). "It has been shown, in cellular and animal models, that changes in TRIB3 expression levels induce systemic insulin resistance." (PMID 23762820, 2013). "No change was observed in Tribbles homolog 3 (TRIB3) that has been linked to insulin resistance and hepatic production of glucose in the liver." (PMID 36835287, 2023). "Insulin resistance caused by the saturated fatty acid palmitic acid also caused ER stress as indicated by an increased mRNA and protein expression of the ER stress-markers ATF6, ATF3, GRP78, CHOP, and Tribbles 3 (TRIB3) in C2C12 myotubes." (PMID 35615361, 2022). "In addition, deletion of Trib3 in mice prevented high-fat diet induced insulin resistance in skeletal muscle." (PMID 35615361, 2022).
Insulin resistance (continued). "Interestingly, PPARα also governs expression in hepatocytes of tribbles pseudokinase 3 (Trib3), a putative protein kinase that promotes insulin resistance in mice and humans." (PMID 28793934, 2017). "Additionally, increased TRIB3 mRNA levels were observed 24 h following polytrauma, the same time when insulin resistance was observed." (PMID 26818585, 2016). "Our data suggests that increased TRIB3 mRNA may indicate a novel role for TRIB3 in acute injury‐induced insulin resistance, which merits further investigation." (PMID 26818585, 2016). "Sitagliptin treatment was able to completely reduce tissue TRIB3 expression, which might be a key mechanism for the decline of insulin resistance and improvement of insulin secretion observed in the diabetic rats under sitagliptin treatment." (PMID 24650557, 2014). "Since TRIB3 induces insulin resistance which would be reversed in part by obestatin, an important question has been whether the TRIB3 polymorphism would determine the level of serum obestatin." (PMID 23245314, 2012). "Moreover, Trib3 expression is involved in hepatic insulin resistance in human subjects." (PMID 39360185, 2024). "Additionally, TRIB3 polymorphisms are associated with T2DM and insulin resistance." (PMID 37083954, 2023). "TRIB3 has been proposed as a key target to treat obesity-related diseases, as many studies have shown that its overexpression prevents the detrimental effects of diet-induced obesity by modulating lipid metabolism, promoting insulin resistance and inhibiting adipocyte differentiation." (PMID 36158793, 2022). "Therefore, PGC-1α promotes liver insulin resistance through PPARα-dependent induction of TRIB3." (PMID 30987128, 2019). "This may suggest a role for TRIB3 in the development of acute insulin resistance following injury." (PMID 26818585, 2016). "TRIB3, thus, is speculated to contribute to insulin resistance." (PMID 23245314, 2012). "Specifically, regarding genes related to insulin resistance pathway, we highlight SOCS3, GSK3B, STAT3, PTEN, TRIB3, FOXO1, and PTPRF, along with MAPK8, which plays a role in metabolic stress and inflammation." (PMID 41282288, 2025). "The data suggest that overnutrition and aging-dependent increases in Trib3 expression are at least partly responsible for the decline in the thermogenic activity of BAT and subsequent obesity and insulin resistance." (PMID 39623091, 2024). "This study aimed to investigate the role of vascular insulin resistance (VIR) and Tribbles homolog 3 (TRIB3) in the pathogenesis of hypoxia-induced pulmonary hypertension (HPH)." (PMID 33192545, 2020).